MGMT (O-6-methylguanine-DNA methyltransferase)
Diseases named in the same sentence as MGMT in open-access papers (continued):
Sharing a sentence is not in itself a finding about the gene and the disease.
glioblastoma (continued). "Promoter methylation of the DNA repair gene O6-methylguanine-DNA methyltransferase (MGMT) is an acknowledged predictive epigenetic marker in glioblastoma multiforme and anaplastic astrocytoma." (PMID 35180887, 2022). "MGMT gene methylation has been investigated in circulating cell-free DNA isolated from the serum of glioblastoma patients." (PMID 35806153, 2022). "In our report, the tumor cells of three patients were positive for MGMT, whose promoter methylation is considered a strong prognostic biomarker in pediatric and adult glioblastoma patients treated with TMZ." (PMID 35991838, 2022). "Mixed-nodular CE in high-grade tumors (GBMs) has been demonstrated to be more frequent in MGMT promoter methylated glioblastoma, whereas ring enhancement is most common in MGMT promoter unmethylated glioblastomas." (PMID 36289752, 2022). "The methylation level at each CpG site correlates with the MGMT messenger RNA (mRNA) expression and survival in patients with glioblastoma." (PMID 36291588, 2022). "Among 321 patients suffering from glioblastoma, we found better survival in patients with glioblastomas that have ≥16% methylation of a particular region of the MGMT gene." (PMID 35804921, 2022). "Even though MGMT promoter methylation in CpG rich sequences and subsequent overexpression is well known for mediating temozolomide resistance in glioblastoma, the clinical relevance of targeting MGMT in MB has only recently emerged." (PMID 35747808, 2022). "Post hoc subgroup analyses of the EF-14 trial revealed an increase in overall survival also for patients with glioblastoma and methylated MGMT promotor." (PMID 35448029, 2022). "Whole-exome sequencing and pathological examination revealed glioblastoma, IDH1 wild type, PTEN deficient, TERT mutated, NF1mutated, MGMT unmethylated." (PMID 36271359, 2022). "Among others, 34–45% of glioblastoma patients present methylated MGMT promoter and it is well documented that epigenetic silencing of MGMT gene correlates with good sensitivity to TMZ treatment." (PMID 35053068, 2022). "Expression of O6-Methylguanosine methyltransferase-MGMT, an important prognostic marker for glioblastoma, was upregulated both at gene and protein levels in U37360 Gy cells, but not in KUGBM840 Gy cells." (PMID 35806055, 2022). "In phase II, patients with the first relapse of MGMT-methylated glioblastoma are screened for the trial." (PMID 35045869, 2022). "Promoter methylation is the main way of silencing the MGMT gene and predicts a favorable outcome in glioblastoma patients treated with alkylating drugs." (PMID 33750464, 2021). "The regulation mechanisms of MGMT expression through its promoter methylation status have been well explored in patients with glioblastoma." (PMID 33397362, 2021). "Of the recently completed studies, two sister trials, CheckMate-49829 and CheckMate-54830, evaluated the addition of PD-1 inhibitor Nivolumab to the adjuvant chemoradiation for glioblastoma with unmethylated and methylated MGMT promoter, respectively." (PMID 33658642, 2021). "Although MGMT promoter status has been shown to be of relevance with respect to treatment and outcome in glioblastoma patients, a consensus on methods and cutoff values to determine MGMT promoter methylation remains to be defined." (PMID 33663593, 2021). "NCT03224104 includes three experimental arms: In Group A, elderly patients with IDH1 wild-type and MGMT unmethylated AA or glioblastoma will receive zotiraciclib and radiation therapy." (PMID 34207158, 2021). "In conclusion, there is a lack of benefit of extending temozolomide treatment for patients with high vascular glioblastomas, even presenting MGMT methylation." (PMID 34771583, 2021). "In this study we investigated the prognostic value of the Ki-67 LI in glioblastoma patients from a population-based cohort including MGMT promoter methylation and post-surgical treatment in the survival analysis." (PMID 34504133, 2021).
glioblastoma (continued). "In Group B, elderly patients with IDH1 wild-type and MGMT methylated AA or glioblastoma will receive zotiraciclib and TMZ." (PMID 34207158, 2021). "Classic genetic analyses in glioblastoma have shown that IDH1 mutation, MGMT promoter methylation, 1p/19q codeletion, G-CIMP methylation, BRAFV600E mutation, and H3K27 mutation are associated with glioblastoma overall survival." (PMID 34732244, 2021). "Even though the survival rate for glioblastoma is very low, chemotherapy provides a guaranteed effect provided patient MGMT methylation status is favourable." (PMID 34830392, 2021). "The survival time of glioblastoma patients with only an IDH1 mutation was shorter than for patients with both IDH1 mutations and MGMT methylation." (PMID 34638714, 2021). "One of the most relevant biomarkers, related with the Stupp treatment efficacy, is MGMT methylation status, present in approximately 50% of glioblastomas." (PMID 34771583, 2021). "Our results show that while sensitizing effects for TMZ-induced toxicities were restricted to MGMT promoter methylated glioblastoma cells, lomustine revealed synergistic cytotoxic effects independent from MGMT promoter methylation status." (PMID 33673490, 2021). "MGMT status is a well-established biomarker for newly diagnosed and recurrent glioblastoma and is predictive for both overall survival and treatment response to temozolomide." (PMID 33937035, 2021). "In conclusion, our results demonstrate the lack of benefit of extending temozolamide treatment in those patients with high vascular glioblastoma, even presenting MGMT methylation." (PMID 34771583, 2021). "The standard of care for newly diagnosed adults with glioblastoma, especially those with MGMT promoter methylated tumors, remains chemoradiation with temozolomide followed by 6 to 12 cycles of adjuvant temozolomide." (PMID 34041027, 2021). "For examples, GLI1 can bind to the promoter region of O6-methylguanine DNA methyltransferase (MGMT) gene to regulate the expression of MGMT and chemotherapy resistance to temozolomide in glioblastoma cells." (PMID 34659557, 2021). "One milestone in glioblastoma therapy was the discovery of the connection between methylation of the MGMT promotor and tumor response to chemotherapy using temozolomide in 2005." (PMID 33963441, 2021). "According to the European Association for Neuro-Oncology (EANO) guideline of 2017, treatment of glioblastoma patients should consider molecular biomarkers like IDH mutation and MGMT promoter methylation." (PMID 32748120, 2021). "Two previous studies reported that patients with MGMT methylated glioblastomas have a higher tendency to develop distant recurrence than those without methylation." (PMID 34784919, 2021). "Temozolomide constitutes the standard chemotherapeutic agent, but only shows limited efficacy in glioblastoma patients with unmethylated O-6-methylguanine-DNA methyltransferase (MGMT) promoter status." (PMID 33673490, 2021). "MGMT promoter methylation is a favorable prognostic factor in glioblastoma, and patients with MGMT promoter methylation benefit from temozolomide." (PMID 34648115, 2021). "Preliminary results suggest that patients with moderate vascularity and methylated MGMT glioblastomas would benefit more from prolonged adjuvant chemotherapy." (PMID 34771583, 2021).
glioblastoma (continued). "The role of MGMT promoter methylation in glioblastoma progression was also assessed among German cases and was shown that there was a correlation between MGMT promoter methylation and survival in newly diagnosed patients." (PMID 33883026, 2021). "This DNA damaging agent is particularly useful in a subclass of glioblastoma cells, those possessing a methylated promoter for the gene of O6-Methylguanine-DNA Methyltransferase (MGMT) that is involved in damage repair induced by alkylating agents." (PMID 33935695, 2021). "Here, we investigated the effects of lomeguatrib treatment in combination with ionizing radiation on MGMT unmethylated human glioblastoma multiforme cell lines." (PMID 34202589, 2021). "Although promising, the level of evidence is low, consisting of small, highly selective, and retrospective series with potential confounding biases related to glioblastoma biology (IDH1/2 mutations status, MGMT promoter methylation status)." (PMID 34200799, 2021). "In this study, we present a potential role of tumor vascularity in the prognostic impact of MGMT methylation status in glioblastoma patients." (PMID 33001310, 2021). "Currently, MGMT methylation is a widely accepted biomarker in glioblastoma, which can predict the effect of chemotherapeutic drugs." (PMID 34305772, 2021). "The most common method of detecting methylation MGMT in glioblastoma is a polymerase chain reaction (PCR) method or combinatorial PCR with MS technology, SYBR Green, or pyrosequencing in glioblastoma patients." (PMID 34210107, 2021). "O-6 Methylguanine-DNA methyltransferase (MGMT) gene promoter methylation is an important biomarker in glioblastoma management." (PMID 34988453, 2021). "In clinical cases, approximately half of glioblastomas express MGMT at the primary tissues, and TMZ is less effective in those cases." (PMID 34073837, 2021). "From the comparison of the three multiparametric Cox survival analyses based on MGMT and rCBVHAT, we conclude that the information provided by both variables are relevant and complementary in predicting the prognosis of glioblastoma patients treated with TMZ." (PMID 33001310, 2021). "MGMT promoter methylation has predictive value in IDH-mutant glioblastoma, but its cutoff value should be higher than that for IDH-wildtype glioblastoma." (PMID 33628600, 2021). "We used an isogenic glioblastoma system (U87) that was modified to overexpress MGMT to investigate the effects of TMZ versus QBS10072S." (PMID 34646647, 2021). "Epigenetic-mediated silencing of the MGMT gene in glioblastoma by promoter methylation has also been shown to correlate with better OS." (PMID 34257620, 2021). "illustrated that miR-370 upregulation recovered the sensitivity of glioblastoma multiforme to temozolomide by impacting MGMT expression." (PMID 34703649, 2021). "Glioblastoma stem cells are reported to abundantly express the MGMT and P-gp proteins, leading to greater resistance to treatment, a higher level of hypoxia, and more frequent tumor recurrence." (PMID 33680961, 2021). "O6methylguanine-DNA methyltransferase (MGMT) promoter methylation is a biomarker widely used to predict the sensitivity of IDH-wildtype glioblastoma to temozolomide therapy." (PMID 33628600, 2021). "Low MGMT levels in other types of cancer have resulted in the consideration of TMZ as a potential therapy beyond glioblastoma and melanoma." (PMID 34676045, 2021). "UA (at 12.5 μM) has also enhanced the cytotoxicity of TMZ in human LN-18 and T98G glioblastoma cells by downregulating MGMT expression, and at 50 mg/kg UA potentiated the efficacy of TMZ in BALB/c mice with LN-18 xenograft." (PMID 33925641, 2021). "Our study measured quantitative MGMT methylation in consecutive glioblastoma patients over 8 years, which allowed better power to examine the interaction between MGMT methylation and temozolomide." (PMID 34988453, 2021).
glioblastoma (continued). "In brain tumors such as glioblastoma, promoter hypermethylation of several genes (MGMT, p16INK4a, TIMP-3, and THBS1) has been detected at high frequencies in serum and CSF." (PMID 34208598, 2021). "We identified HOTAIRM1 as a candidate lncRNA whose up-regulation is significantly associated with shorter survival of glioblastoma patients, independent from IDH mutation and MGMT promoter methylation." (PMID 34584066, 2021). "In a cohort of newly diagnosed glioblastoma patients treated with stereotactic biopsy or open tumor resection plus concomitant chemoradiotherapy, we assessed MGMT-promoter methylation by methylation-specific polymerase-chain-reaction (MSP)." (PMID 33663593, 2021). "Although O-6-methylguanine–DNA methyltransferase (MGMT) promote methylation and the status of the IDH1 mutation seem to show correlation with longer survival, recurrence of glioblastoma patients is almost common." (PMID 33525678, 2021). "The study confirmed no adverse effects after the use of metformin, confirming its safety and tolerability and validating previous results on favorable outcomes of glioblastoma patients, particularly those with low methylation levels of MGMT (NCT02780024)." (PMID 35008275, 2021). "Given that the IDH status has critical effects on the survival and epigenetic features of glioblastoma, we aimed to assess the role of MGMT promoter methylation in IDH-mutant glioblastoma." (PMID 33628600, 2021). "An epimutation in the promoter region of the MGMT gene is one of the most important prognostic factors for patients with glioblastoma and it can predict the response to treatment with alkylating agents such as temozolomide." (PMID 34638292, 2021). "Our assay will improve the therapeutic management of glioblastoma patients, being a more sensitive and competitive alternative methodology that ensures the standardization of the MGMT-biomarker making it reliable and suitable for clinical use." (PMID 33750464, 2021). "During and after this period, neuro-oncological treatment of glioblastomas has progressed, e.g. the advent of chemotherapy with TMZ and CCNU for patients with MGMT promoter-methylated glioblastoma as well as the introduction of tumour-treating fields." (PMID 32748120, 2021). "Using isogenic TMZ-sensitive and TMZ-resistant human glioblastoma cells, we report that the expression of O6-methylguanine DNA methyltransferase (MGMT), which is known to repair TMZ-induced DNA methylation, does not primarily account for TMZ resistance." (PMID 34769368, 2021). "Younger patients with glioblastoma have better outcomes when IDH1/2 mutations and MGMT promoter methylation are present, so an accurate diagnosis is critical for these patients." (PMID 33506208, 2021). "Compared with IDH-wildtype glioblastomas, IDH-mutant glioblastomas showed significantly higher (P < 0.0001) MGMT promoter methylation." (PMID 33628600, 2021). "Our results are in accordance with previous findings that resistance to TMZ in 3D glioblastoma cultures increases due to the elevated MGMT expression levels." (PMID 34439644, 2021). "Among the 191 patients with methylated glioblastoma, the median MGMT methylation was 30.0% (IQR 16–42.8%)." (PMID 34988453, 2021). "Glioblastoma patients whose tumors carried an IDH1 mutation, MGMT promoter methylation and low HOTAIRM1 expression showed the longest overall survival." (PMID 34584066, 2021). "A first-in-human phase I study of liposomal RNA vaccines for newly diagnosed adult O6-methylguanine-DNA methyltransferase (MGMT) unmethylated glioblastoma (GBM) have recently begun recruiting." (PMID 35056922, 2021). "As was expected from the literature, we observe a significant prognostic impact of MGMT methylation in glioblastoma patients treated with TMZ included in the NCT03439332 multicenter international dataset." (PMID 33001310, 2021).
glioblastoma (continued). "Despite the well-documented impact of MGMT methylation on the prognosis of glioblastoma patients treated with TMZ, the survival of these patients is not explained by this factor alone." (PMID 33001310, 2021). "Additional studies have also described not only a predictive, but also a prognostic role of MGMT methylation for glioblastoma patients." (PMID 33001310, 2021). "In this study, we evaluated the impact of MGMT promoter methylation and IDH1 mutation on the recurrence-free interval in patients with glioblastoma treated with different treatment modalities (radiotherapy and different types of chemotherapies)." (PMID 34257620, 2021). "MGMT directly demethylates O6-meG and is downregulated in about 45% of glioblastoma patients with MGMT promoter methylation in the tumor and enhanced temozolomide sensitivity." (PMID 34827559, 2021). "In older patients presenting with wtIDH glioblastoma, the presence of MGMT promoter methylation predicts a positive response to therapy and longer survival." (PMID 34439271, 2021). "Low MGMT expression via promoter methylation is a generally accepted predictive biomarker in TMZ-treated glioblastoma and has been proposed as a useful biomarker for patient stratification." (PMID 34676045, 2021). "Our data confirm impact of MGMT promoter methylation in patients with glioblastoma, IDH-wildtype on OS and PFS." (PMID 34185258, 2021). "Similar results were obtained when MGMT status was included and when IDH-mutated glioblastomas were excluded (HR = 1.23, p = 0.23)." (PMID 34504133, 2021). "In conclusion, our model predicts MGMT promoter methylation status based on tumor texture features on gadolinium-enhanced T1-weighted MRI in patients with recurrent glioblastoma treated with alkylating chemotherapy." (PMID 33937035, 2021). "On the other hand, as shown in a phase III study, MGMT promoter methylation predicted the value in patients with glioblastoma treated with alkylating drugs such as temozolomide." (PMID 34412691, 2021). "The MGMT promoter methylation status is a predictive biomarker that can be used for treatment allocation in patients with glioblastoma." (PMID 33941250, 2021). "Our results confirmed two previous imaging studies and showed that methylated glioblastoma patients with MGMT had a greater tendency to develop out-of-field recurrence than those with unmethylated status." (PMID 34098965, 2021). "A reported mechanism of temozolomide chemosensitization by disulfiram has been identified in pituitary adenoma stem-like cells and in glioblastoma cell lines: disulfiram covalently modifies MGMT, leading to the proteasomal degradation of the DNA repair enzyme." (PMID 34827559, 2021). "Promotor methylation of the MGMT gene is a strong predictor of therapy response and survival in patients with glioblastoma and has been suggested as a prognostic biomarker for high-risk dLGG treated with RT and TMZ." (PMID 33941250, 2021). "The histopathological diagnosis confirmed the nature of glioblastoma grade IV, IDH wild type, TERT promoter mutated, and MGMT wild type." (PMID 33716935, 2021). "The second one combined nivolumab with radiotherapy in CheckMate-498 trial (NCT02617589) but also failed to significantly improve OS of patients with newly diagnosed MGMT-unmethylated glioblastoma, in comparison to chemo-radiotherapy with TMZ." (PMID 33680090, 2021). "Accordingly, several quantitative radiomic approaches have shown their potential to predict MGMT status and clinical outcome in patients with newly diagnosed glioblastoma." (PMID 33937035, 2021). "The MGMT enzyme repairs the DNA damage caused during temozolomide (TMZ) therapy and therefore is responsible for drug resistance of glioblastoma cells to anticancer treatments." (PMID 34203660, 2021). "Use of IDH1 combined with MGMT promoter as a stratification factor seems appropriate in clinical trials for the treatment of patients with secondary glioblastoma." (PMID 34257620, 2021).